CELF2 (CUGBP Elav-like family member 2)
Description:
RNA-binding protein implicated in the regulation of several post-transcriptional events. Involved in pre-mRNA alternative splicing, mRNA translation and stability. Mediates exon inclusion and/or exclusion in pre-mRNA that are subject to tissue-specific and developmentally regulated alternative splicing. Specifically activates exon 5 inclusion of TNNT2 in embryonic, but not adult, skeletal muscle. Activates TNNT2 exon 5 inclusion by antagonizing the repressive effect of PTB. Acts both as an activator and as a repressor of a pair of coregulated exons: promotes inclusion of the smooth muscle (SM) exon but exclusion of the non-muscle (NM) exon in actinin pre-mRNAs. Promotes inclusion of exon 21 and exclusion of exon 5 of the NMDA receptor R1 pre-mRNA (By similarity). Involved in the apoB RNA editing activity. Increases COX2 mRNA stability and inhibits COX2 mRNA translation in epithelial cells after radiation injury (By similarity). Binds to the muscle-specific splicing enhancer (MSE) intronic sites flanking the TNNT2 alternative exon 5. Binds preferentially to UG-rich sequences, in particular UG repeat and UGUU motifs. Binds to apoB mRNA, specifically to AU-rich sequences located immediately upstream of the edited cytidine. Binds AU-rich sequences in the 3'-UTR of COX2 mRNA (By similarity). Binds to an intronic RNA element responsible for the silencing of exon 21 splicing (By similarity). Binds to (CUG)n repeats. May be a specific regulator of miRNA biogenesis. Binds to primary microRNA pri-MIR140 and, with CELF1, negatively regulates the processing to mature miRNA.
Synonyms: CELF-2; CUG-BP2; ETR-3; BRUNOL3; CUGBP2; ETR3; NAPOR; NAPOR-2; DEE97
Tractability: PROTAC: ubiquitination databases record sites on it; its protein half-life has been measured.
Gene: Protein-coding gene on chromosome 10 (10,798,397 to 11,336,675, forward strand). Ensembl gene ENSG00000048740.
Subcellular location: Nucleus; Cytoplasm
Subcellular location (Human Protein Atlas): Nucleoplasm; Midbody ring; Vesicles
Gene Ontology:
Molecular function: pre-mRNA binding; RNA binding; mRNA 3'-UTR binding; nucleic acid binding
Biological process: mRNA splice site recognition; regulation of alternative mRNA splicing, via spliceosome; regulation of heart contraction; RNA processing
Cellular component: nucleoplasm; nucleus; cytoplasm; ribonucleoprotein complex
Genetic constraint (gnomAD): Loss-of-function variants: 8 observed, 49.15 expected, observed/expected ratio (o/e) 0.16, 90% interval 0.095 to 0.29. The upper end of that interval is the gene's LOEUF score, 0.29, which puts it in group 1 of 6, group 1 being the genes least tolerant of losing a copy. Missense variants: 303 observed, 575.32 expected, observed/expected ratio (o/e) 0.53, 90% interval 0.48 to 0.58. Synonymous variants: 237 observed, 226.7 expected, observed/expected ratio (o/e) 1.05, 90% interval 0.94 to 1.16.
Homologues: Orthologues: chimpanzee CELF2 (99% identical), macaque CELF2 (99% identical), guinea pig CELF2 (95% identical), rabbit CELF2 (95% identical), mouse Celf2 (95% identical), dog CELF2 (94% identical), rat Celf2 (94% identical), tropical clawed frog celf2 (93% identical), zebrafish celf2 (87% identical), Drosophila melanogaster bru2 (51% identical), Drosophila melanogaster bru1 (49% identical), Drosophila melanogaster Pof (18% identical), and 3 more. Paralogues in human: CELF1 (75% identical), CELF3 (44% identical), CELF4 (44% identical), CELF5 (43% identical), CELF6 (43% identical), RBM28 (22% identical).
Diseases named in the same sentence as CELF2 in open-access papers:
CELF2 is named in the same sentence as 77 diseases in open-access papers, as found by Europe PMC text mining. Sharing a sentence is not in itself a finding about the gene and the disease. The quoted sentences say what the papers report.
breast carcinoma (16 papers, 2021 to 2025). "CELF2 is a crucial splicing factor, and its downregulation has been reported to promote tumor progression in both pancreatic and breast cancers." (PMID 40990037, 2025). "This oncogenic function of CELF2 contrasts with its repressive effect on cell proliferation previously reported in various cancers such as breast cancer, non-small-cell lung carcinoma or even glioma, where CELF2 is underexpressed." (PMID 37894405, 2023). "Promoter DNA methylation silences exon inclusion-regulator CUGBP Elav-like family member 2 (CELF2) expression in pancreatic, gastric and breast cancer cells, and epigenetic silencing of CELF2 is associated with poor patient prognosis." (PMID 37506056, 2023). "The CELF2 gene is silenced in human breast cancer by promoter hypermethylation, and the restoration of its expression reduces cell proliferation; this allowed the authors to propose that CELF2 behaves as a tumor suppressor." (PMID 35158828, 2022). "CELF2, an RNA binding protein involved in alternative splicing, has also been reported to be involved in breast cancer growth and progression." (PMID 33461604, 2021). "To better understand the specific mechanism by which CELF2 affects prognosis in breast cancer, by integrating clinicopathological information from the Kaplan‐Meier plotter database, we explored the prognostic value of CELF2 in stratified populations." (PMID 34288370, 2021). "Previously, it was revealed that CELF2 suppression by promoter hypermethylation in breast cancer cells induces modulations of intron retention patterns and isoform imbalance in many target genes." (PMID 34681716, 2021). "In breast cancer, CELF2 overexpression suppresses proliferation and invasion, and inhibits tumor growth and angiogenesis." (PMID 34681716, 2021). "As we found CELF2 was significantly down‐regulated in breast cancer, and its expression was closely related to better prognosis." (PMID 34288370, 2021). "Previous studies have demonstrated that CELF2 could play an important role in many kinds of tumors, including liver cancer, ovarian cancer, breast cancer, and gastric cancer." (PMID 35941702, 2022). "Notably, CELF2 expression was much higher in basal‐like breast cancer (also known as TNBC) than in luminal and HER2 subtype." (PMID 34288370, 2021). "Specifically, high CELF2 expression was dramatically associated with prolonged OS and RFS in breast cancer patients with ER negative, PR negative, HER2 negative, lymph node positive and grade 3 (OS and RFS: HR <1 and p < 0.05)." (PMID 34288370, 2021). "Furthermore, high CELF2 expression was associated with significantly prolonged OS and RFS of breast cancer patients with ER, PR and HER2 negative, lymph node metastasis and higher grade." (PMID 34288370, 2021).
colon cancer (10 papers, 2014 to 2024). "In the literature, the Coiled-coil domain containing 3 (CCDC3) represses tumor necrosis factor-α/nuclear factor κB-induced endothelial inflammation and the CELF2 is associated with T-cell signaling and it is also a suppressor gene of colon cancer." (PMID 26635870, 2015). "CELF2 functions as a tumor suppressor in multiple cancers including non-small cell lung carcinoma and colon cancer." (PMID 39408753, 2024). "The well-known tumor suppressor gene CELF2 plays an essential role in colon cancer initiation and progression." (PMID 35884370, 2022). "On the contrary, CELF2 is a putative tumor suppressor in colon cancer, overexpression of CELF2 results in reduced colony formation and apoptosis by mitotic catastrophe in pancreatic and colon cancer cells." (PMID 31534127, 2019). "In colon cancer cells, CELF2 expression is consistently reduced during neoplastic transformation, and suppression of CELF2 expression decreased radiation-induced apoptosis, suggesting it is a potential tumor suppressor protein." (PMID 26314850, 2015). "The family comprises six members including CELF2, which functions as a tumor suppressor in colon cancer." (PMID 24886479, 2014).
glioma (9 papers, 2016 to 2025). A benign or malignant brain and spinal cord tumor that arises from glial cells (astrocytes, oligodendrocytes, ependymal cells). "In this study, we have identified the protein CELF2 as being an efficient epigenetic regulator of genes in glioma stem cells (GSCs)." (PMID 37894405, 2023). "This functional discordance of CELF2 is exemplified by its good prognostic value in low-grade gliomas, whereas it is of poor prognosis in classical GBM subtypes not methylated on the MGMT promoter." (PMID 37894405, 2023). "So far, convincing studies in various cancers, including gliomas, have shown that CELF2 plays the role of tumor suppressor." (PMID 37894405, 2023). "Downregulation of miR-95 has been shown to affect glioma cell proliferation, invasion and apoptosis by targeting CELF2." (PMID 36354672, 2022). "CELF2 siRNAs were transfected into glioma cells to specifically inhibit the increase in CELF2 expression induced by ASO‐miR‐363‐3p." (PMID 34636136, 2021). "We measured the expression of CELF2 and five candidate miRNAs by qRT‐PCR in 18 glioma samples collected from the Department of Neurosurgery of the Second Affiliated Hospital of the Hebei Medical University." (PMID 34636136, 2021). "For the first time, we provided evidence that miR‐363‐3p induces the epithelial‐to‐mesenchymal transition (EMT) in glioma cells via the Wnt/β‐catenin pathway by targeting CELF2." (PMID 34636136, 2021). "In glioma cells, CELF2 is a potential target of miR-20a and miR-95-3p, in which the overexpression of these two miRNAs is positively correlated with cell proliferation and invasion." (PMID 34681716, 2021). "We measured expression levels of CELF2 and each miRNA candidate in 18 glioma samples to determine their possible correlation." (PMID 34636136, 2021). "We observed an abnormal expression pattern of CELF2 in glioma cells, and higher CELF2 expression correlated with better prognosis." (PMID 34636136, 2021). "In conclusion, miR‐363‐3p induced the EMT, which resulted in increased migration and invasion and reduced apoptosis in glioma cell lines, via the Wnt/β‐catenin pathway by targeting CELF2." (PMID 34636136, 2021). "We subsequently designed rescue assays to confirm that miR‐363‐3p regulated glioma cell biological properties by targeting CELF2." (PMID 34636136, 2021). "Regulatory network of splicing factors and prognostic splicing events were shown; suggesting hub splicing factors including SNRPB and CELF2 were participating in splicing regulatory in glioma." (PMID 31729991, 2019). "Analyses correlating the expression of CELF2 against the expression of all 789 public NJs identified a greater percentage of NJs whose expression generally increased (average Pearson correlation coefficient of >0.10) with the increasing level of CELF2 expression across all glioma subtypes." (PMID 39972144, 2025). "However, nothing has yet been reported on CELF2 expression and function in the context of intra-tumoral glioma heterogeneity and, more specifically, in patient-derived glioma stem cells (GSCs) and their differentiated counterparts." (PMID 37894405, 2023). "Furthermore, when we increased the expression level of miR‐363‐3p in glioma cell lines, we observed decreased level of CELF2 mRNA." (PMID 34636136, 2021). "In our previous study, we reported that CELF2 has a tumour‐suppressive function in glioma." (PMID 34636136, 2021). "In our previous study, we demonstrated a tumour‐suppressive function of CELF2 in glioma cells." (PMID 34636136, 2021). "We also found SNRPB and CELF2 as hub splicing factors of prognostic splicing events, indicating that these splicing factors might be potential targets for glioma treatment." (PMID 31729991, 2019). "In addition, CELF2 has been identified as one of the hub splicing factors of prognostic splicing events, suggesting that these splicing factors might be used to treat glioma." (PMID 34681716, 2021). "Hence, we focussed on the relationship between CELF2 and miR‐363‐3p in glioma cells." (PMID 34636136, 2021).
glioma (continued). "The bioinformatic analysis confirmed using a luciferase reporter assay showed that miR-20a can directly and negatively regulate CELF2 (CUGBP Elav-like family member 2) gene expression, thus playing a critical role in the growth and invasion of glioma cells." (PMID 36321132, 2022). "This study was designed to uncover the role of miR‐363‐3p as a negative modulator of CELF2 expression in the development of glioma." (PMID 34636136, 2021). "In conclusion, our experiments in glioma cell lines showed that miR‐363‐3p induced the EMT, which resulted in increased migration and invasion and reduced apoptosis via the Wnt/β‐catenin pathway by targeting CELF2." (PMID 34636136, 2021). "While CELF2 expression is a marker of good prognosis in low-grade glioma, we found conversely that CELF2 had no prognostic value in GBMs, with the exception of classical non-methylated subtypes on the promoter of MGMT, where high CELF2 expression was of poor prognosis." (PMID 37894405, 2023).
ovarian carcinoma (9 papers, 2021 to 2024). A malignant neoplasm originating from the surface ovarian epithelium. "Nonetheless, in contradiction to these findings, the expression of CELF2 was shown to positively correlate with better prognosis in ovarian cancer patients." (PMID 39456618, 2024). "The expression of CELF2 was down-regulated in ovarian cancer cells, and led to over-proliferation, migration, and invasion of ovarian cancer cells in vitro and in vivo." (PMID 38514854, 2024). "CELF2 was found to bind to and stabilise FAM198B mRNAs, suggesting an CELF2/FAM198B axis as a therapeutic target for ovarian cancer treatment." (PMID 34328175, 2021). "CELF2 increases the stability of the tumor suppressor FAM198B in ovarian cancer by binding to AU/U-rich elements in the 3′UTR regions." (PMID 34681716, 2021). "CELF2 can also influence ovarian cancer cell proliferation, migration, and invasion, making it more susceptible to cisplatin." (PMID 34681716, 2021). "In ovarian cancer, CELF2 could stabilize FAM198B mRNA by binding to AU/U-rich elements (AREs) in the 3’UTR." (PMID 34295816, 2021).
gastric cancer (8 papers, 2020 to 2022). A primary or metastatic malignant neoplasm involving the stomach. "CELF2 downregulation has been confirmed to promote the occurrence and development of gastric malignant tumors." (PMID 35941702, 2022). "In gastric cancer, the inhibition of CELF2 by miR-615-3p enhances proliferation and migration while blocking apoptosis." (PMID 34681716, 2021). "Interaction of hsa-miR-375 with both APH1B and CELF2 was experimentally confirmed in a gastric carcinoma sample." (PMID 34683087, 2021). "Conversely, in gastric cancer, the expression of CELF2, along with BAG2 (BAG Cochaperone 2), RBFOX2 (RNA Binding Fox-1 Homolog 20), and PTBP2 (Polypyrimidine Tract Binding Protein 2) splicing factors are associated with poor prognosis and alternative splicing events." (PMID 34681716, 2021). "CELF2 suppression promotes gastric cancer cell proliferation and migration." (PMID 34692669, 2021). "Notably, CELF2, RBFOX2, PTBP2 and QKI were also involved in the misregulation of AS events in Epstein-Barr virus-associated gastric carcinomas." (PMID 33186122, 2020). "CELF2 is an RNA-binding protein of the CELF family that acts as a tumor suppressor and is positively correlated with the prognosis of various tumors, such as non-small cell lung carcinoma, gastric cancer, and pancreatic cancer." (PMID 32984057, 2020).
hepatocellular carcinoma (8 papers, 2015 to 2024). A malignant tumor that arises from hepatocytes. "LncRNA MRVI1-AS1 was found to accelerate hepatocellular carcinoma progression by recruiting the RNA-binding protein CELF2 to stabilize SKA1 mRNA." (PMID 39194582, 2024). "CELF2 has been shown to be a miR-95 downstream target and Brucein-D, a drug that targets miR-95 and reduces hepatocellular carcinoma (HCC) cell proliferation in vitro and tumor growth in vivo." (PMID 34681716, 2021). "Three splicing factors, CELF2, ESRP2 (epithelial splicing regulatory protein 2), and SRSF5 (serine- and arginine-rich splicing factor 5), which are substantially downregulated in hepatocellular carcinoma samples, were found to be responsible for splicing dysregulation in hepatocellular carcinoma." (PMID 34681716, 2021).
pancreatic cancer (8 papers, 2011 to 2026). "Consequently, CELF2 promotes the conversion of CD44s to CD44v isoform, which acts as a regulator that protects against the progression of pancreatic cancer through the endoplasmic reticulum‐associated degradation signalling pathway." (PMID 37850412, 2023). "We further detected the mRNA expression levels of ALKBH5 and CELF2 in pancreatic cancer tissues, and found that the CELF2 expression level is positively correlated with the ALKBH5 expression level." (PMID 35941702, 2022). "Curcumin suppresses pancreatic tumor development by raising the expression of CELF2, which prevents COX-2 and VEGFA (Vascular Endothelial Growth Factor A) mRNAs from being translated." (PMID 34681716, 2021). "Finally, CELF2 promotes pancreatic cancer tumorigenesis and metastasis via Endoplasmic-reticulum-associated protein degradation (ERAD)." (PMID 38902676, 2024). "Similarly, the upregulation of CELF2 increases the response of pancreatic cancer cells to chemotherapy." (PMID 34681716, 2021). "Supportively, overexpression of CELF2 resulted in mitotic catastrophe of pancreatic cancer cells." (PMID 26314850, 2015). "Additionally, ALKBH5‐mediated m6A demethylation reduces the mRNA stability of CELF2, a splicing factor involved in mRNA splicing, translation and editing, thus highlighting the indirect effect of ALKBH5 on splicing events in pancreatic cancer." (PMID 37850412, 2023).
glioblastoma (4 papers, 2021 to 2025). The most malignant astrocytic tumor (WHO grade IV). "Indeed CELF proteins are mainly considered as tumour suppressors, TCGA data show that CELF2 expression is associated with shorter overall survival in invasive breast carcinoma, low-grade glioma and glioblastoma." (PMID 36528833, 2023). "Profiling of miRNA populations from human glioma tissues and glioblastoma cell lines identified the upregulation of several miRNAs that are predicted to target CELF2." (PMID 34769047, 2021). "Subsequent research utilizing luciferase assays with miR-95-3p and miR-20a provided substantial evidence of their role in CELF2 inhibition, promotion of tumor development, and progression in glioblastomas." (PMID 34769047, 2021). "Dysregulation of CELF2 has been described in several cancers, particularly glioblastomas." (PMID 34769047, 2021).